ELK3 (ETS transcription factor ELK3)
Diseases named in the same sentence as ELK3 in open-access papers (continued):
Sharing a sentence is not in itself a finding about the gene and the disease.
glioma (6 papers, 2021 to 2025). A benign or malignant brain and spinal cord tumor that arises from glial cells (astrocytes, oligodendrocytes, ependymal cells). "Kaplan-Meier and Cox regression analyses demonstrated that a high ELK3 expression was markedly associated with low patient survival and served as an independent biomarker of gliomas." (PMID 34976781, 2021). "The results demonstrated that ELK3 expression had a prognostic value for 1-year, 3-year, and 5-year survival rates in patients with gliomas, with abnormally high expression associated with reduced survival." (PMID 34976781, 2021). "Here, abnormally high expression of ELK3 in gliomas clinical samples was associated with reduced survival time in gliomas patients, as evidenced by analyses using multiple databases." (PMID 34976781, 2021). "ELK3 participates in the regulation of mitochondrial metabolism regulation, and its expression has been found to be associated with a poor prognosis in patients with gliomas." (PMID 39217365, 2024). "Moreover, increased ELK3 expression in clinical samples of glioma was associated with reduced overall survival at the 1-, 3- and 5-year intervals." (PMID 36425564, 2022). "Therefore, our work aimed to explore the expression level of ELK3 in gliomas and its potential diagnostic and therapeutic value in gliomas." (PMID 34976781, 2021). "The univariate and multivariate analyse using Cox regression revealed that high ELK3 expression might be an independent risk factor for poor diagnosis and prognosis of gliomas." (PMID 34976781, 2021). "Thus, it is plausible that ELK3 acts as a carcinogenic gene in the progression of gliomas and that high expression of ELK3 may be an independent risk factor for poor diagnosis and prognosis of patients with gliomas." (PMID 34976781, 2021). "Further studies revealed that ELK3 knockdown decreased the proliferation and migration of a glioma cell line in vitro, highlighting the role of this marker in the pathogenesis of glioma." (PMID 36425564, 2022). "Second, analysis based on two datasets from the GEO database, GSE4290 and GSE50161, indicated that ELK3 expression was also higher in gliomas than in normal brain tissues." (PMID 34976781, 2021). "This study is the first to analyze and discover that ELK3 is abnormally high in gliomas and closely related to the poor prognosis of patients with gliomas comprehensively and systematically." (PMID 34976781, 2021). "We not only studied the role of ELK3 as a carcinogenic gene in the occurrence and development of gliomas, but also identified four small-molecule compounds with inhibitory effects on ELK3: sanguinarine, omeprazole, rimexolone, and phthalylsulfathiazole." (PMID 34976781, 2021). "Using the GEPIA database, we found that ELK3 was abnormally overexpressed in gliomas compared with normal brain tissue." (PMID 34976781, 2021). "First, based on multiple databases, we found that ELK3 overexpression was closely related to the poor prognosis of patients with gliomas, based on CGGA RNG-seq (P < 0.001), CGGA microarray (P < 0.001), and TCGA RNA-seq (P < 0.001) databases." (PMID 34976781, 2021). "The relationships between abnormally high expression of ELK3 and the clinical characteristics of patients with gliomas were elucidated using the CGGA RNA-seq, CGGA microarray, and TCGA RNA-seq databases." (PMID 34976781, 2021). "We also conducted related studies by western blotting to explore the regulation mode of ELK3 on JAK2–STAT3 expression in gliomas." (PMID 34976781, 2021). "Wilcox and Kruskal-Wallis tests revealed that expression of ELK3 was positively correlated with several clinical characteristics of patients with gliomas, such as age, WHO classification, and recurrence." (PMID 34976781, 2021).
glioma (continued). "Here, although we used multiple well-known databases to explain the expression pattern of ELK3 in gliomas and its relationship with multiple malignant characterizations of gliomas, and verified it experimentally, there are still some unavoidable limitations." (PMID 34976781, 2021). "Third, the results based on the HPA database revealed that the protein expression level of ELK3 in gliomas tissues was markedly higher than that in normal brain tissues." (PMID 34976781, 2021). "The expression of ELK3 in gliomas was verified based on the analysis results of GEO database and HPA database and RT-qPCR results." (PMID 34976781, 2021). "To observe the effect of ELK3 knockdown on the proliferation and migration of glioma cells, we used the screened siRNA sequence to target the downregulation of ELK3 expression in U251 cells." (PMID 34976781, 2021). "In vitro experiments reveal that ELK3 overexpression can increase the proliferation and migration of gliomas cells and play a role through the regulation of JAK2 the STAT3 signaling pathway." (PMID 34976781, 2021). "We revealed the putative mechanism of ELK3 involvement in malignant gliomas progression and identified a new and efficient biomarker for glioma diagnosis and targeted therapy." (PMID 34976781, 2021). "The results based on different databases suggested that ELK3 had a reliable value in predicting the prognosis of glioma patients." (PMID 34976781, 2021). "This study aimed to comprehensively and systematically reveal the correlation between ELK3 and the malignant progression of gliomas by analyzing clinical sample information stored in multiple databases." (PMID 34976781, 2021). "Based on the sample data from multiple databases and real-time quantitative polymerase chain reaction (RT-qPCR), the abnormally high expression of ELK3 in gliomas was confirmed." (PMID 34976781, 2021). "ELK3 has been identified as a susceptibility locus for childhood acute lymphoblastic leukemia (ALL) and several studies showed that ELK3 plays a critical oncogenic role in various cancers, including glioma, pancreatic, and gastric cancers." (PMID 40435251, 2025). "Likewise, the ETS transcription factor ELK3 was also recently identified as a novel oncogene in gliomas." (PMID 36425564, 2022). "ELK3 was overexpressed in gliomas compared with normal brain tissue based on database analysis." (PMID 36425564, 2022). "To explore the specific mechanism of ELK3 as an oncogene in the progression of gliomas, we explored the cell signaling pathways that ELK3 may participate in gliomas through GSEA, and investigated its functions." (PMID 34976781, 2021). "Finally, we explored the predictive value of ELK3 for the prognosis of patients with gliomas using receiver operating characteristic curve (ROC) analysis." (PMID 34976781, 2021). "Moreover, Cell Counting Kit‐8 (CCK-8), immunofluorescence, and wound healing assays confirmed that ELK3 overexpression markedly promoted the proliferation and migration of glioma cells." (PMID 34976781, 2021). "Based on above results, we speculated that ELK3 overexpression might promote the malignant growth, proliferation, and migration of gliomas through regulating expression of JAK2 and STAT3, especially STAT3." (PMID 34976781, 2021). "The high correlation between ELK3 and the malignant phenotype of gliomas revealed in our study may be of great significance for gene-targeted therapy of gliomas." (PMID 34976781, 2021). "Therefore, it is plausible that ELK3, as an oncogene, is closely related to adverse clinical features of gliomas." (PMID 34976781, 2021). "Consequently, we intend to determine the mechanism by which ELK3 participates in the pathological process and malignant progression of gliomas." (PMID 34976781, 2021). "To study whether changing the expression pattern of ELK3 will change the proliferation and migration ability of gliomas cells, we targeted knockdown expression of ELK3 in U251 cells using cell transfection technology." (PMID 34976781, 2021).
glioma (continued). "GSEA analysis showed that ELK3 might promote the malignant progression of gliomas through JAK-STAT signaling pathway." (PMID 34976781, 2021). "Therefore, we suggest that ELK3 is a prognostic marker with a great potential for glioma angiogenesis and ELK3-targeted therapeutic strategies might hold promise in improving the efficacy of anti-angiogenic therapies." (PMID 37452291, 2023). "Hence, overexpression of ELK3 markedly promoted the proliferation and migration of gliomas cells." (PMID 34976781, 2021). "Therefore, based on the analysis of large numbers of samples from multiple databases, we explored, for the first time, the correlations of ELK3 with the clinical features of gliomas as well as the pathological process and the potential mechanism of ELK3’s involvement in multi-level gliomas." (PMID 34976781, 2021). "Whether ELK3 promotes malignant progression of glioma requires further study." (PMID 34976781, 2021). "Therefore, we speculated that ELK3 might be involved in the pathological process of gliomas as an oncogene and aimed to reveal the relationship between ELK3 expression and gliomas prognosis." (PMID 34976781, 2021). "Therefore, ELK3 may serve as an efficient biomarker for the diagnosis and prognosis of gliomas and it can also be used as a therapeutic target to improve the poor prognosis of patients with gliomas." (PMID 34976781, 2021). "However, it remains unclear whether ELK3, as a key gene, affects the pathological process of gliomas and the prognosis of patients with gliomas." (PMID 34976781, 2021). "Hence, we generated ROC of ELK3 expression in gliomas to analyze its prognostic value in gliomas." (PMID 34976781, 2021). "Thus, the impact of ELK3 on the occurrence and progression of gliomas remains unclear." (PMID 34976781, 2021). "To further demonstrate how ELK3 regulates these pathways to affect the malignant progression of gliomas, we explored the regulation of JAK2/STAT3 by ELK3 through western blot experiments." (PMID 34976781, 2021). "Using microarray datasets from patients with different grades of glioma, we have analyzed the expression profiles of various ETS genes, and have identified ETV1, ELK3, ETV4, ELF4, and ETV6 as novel biomarkers for the identification of different glioma grades." (PMID 33671331, 2021). "We show that, while ETV1 is expressed at high levels in grade 2 glioma, its expression gradually decreases with glioma stage, and on the other hand, ELK3 and ETV4 expressions are increased with progression of the glioma stage." (PMID 33671331, 2021). "To explore the mechanism by which ELK3, as an oncogene, affects the pathological process and malignant progression of gliomas, we used GSEA to identify the possible signaling pathways of ELK3 in gliomas." (PMID 34976781, 2021). "Although ELK3 is well known to be related to cell transfer and invasion and plays a crucial role in the occurrence or evolution of malignant tumors, no research on ELK3 in gliomas has been reported." (PMID 34976781, 2021). "The expression of ELK3, ETV4, and to some extent ELK4 was found to increase gradually with glioma grade, while ETV1 expression was highest in grade 2 glioma, and progressively decreased with glioma stage." (PMID 33671331, 2021). "However, whether ELK3 affects the pathological process of gliomas has not been elucidated." (PMID 34976781, 2021). "ELK3 expression is reportedly higher in 1p/19q non-codeletion and IDH wild-type gliomas than in other gliomas types, suggesting that ELK3 expression is positively correlated with the malignant degree of gliomas." (PMID 34976781, 2021).
liver cancer (6 papers, 2020 to 2022). An epithelial or non-epithelial malignant neoplasm that arises from the liver. "ETS transcription factor ELK3 (ELK3) plays a pivotal role in promoting the progression and metastasis of a number of types of cancer, including breast, prostate, bladder and liver cancer." (PMID 35409069, 2022). "ELK3 has been reported to participate in cancer genesis and development, including gastric, breast, and liver cancers." (PMID 36243865, 2022). "ELK3 elevates the expression of HIF-1α and promotes the migration of liver cancer stem cells." (PMID 34917613, 2021).
prostate carcinoma (6 papers, 2013 to 2024). A carcinoma that arises from epithelial cells of the prostate gland. "Four SNPs in three genes (COL4A3, PDGFD and ELK3) were associated with prostate cancer aggressiveness in both the CGEMS and Moffitt groups with a p-value less than 0.05." (PMID 23593148, 2013). "The CC and CT genotype of rs2268509 in the ELK3 was positively associated with prostate cancer aggressiveness (OR = 1.29, p-value = 0.047 for CGEMS; OR = 1.57, p-value = 0.002 for Moffitt)." (PMID 23593148, 2013). "Another study reported that a blocking agent suppressed Ras/Erk-ELK3 signaling and also inhibited the progression of prostate cancer, suggesting that ELK3 is a promising target molecule for preventing cancer metastasis." (PMID 35409069, 2022). "In prostate cancer studies, it has been shown that inhibition of ELK3 can promote cycle arrest and apoptosis of tumor cells." (PMID 34233659, 2021). "We showed that silencing of ELK3 by siRNA in prostate cancer cell DU145 induced S-M phase arrest, promoted apoptosis, inhibited cell proliferation and migration in vitro, and suppressed xenograft growth in mice in vivo." (PMID 32104682, 2020). "Moreover, the ELK3 protein half-life was notably extended in SPOP knockdown Du145 prostate cancer cells." (PMID 38632244, 2024). "The contribution of ELK3 to prostate cancer progression was investigated in the present study." (PMID 32104682, 2020). "In conclusion, modulation of ELK3 expression may control the progression of prostate cancer partly by regulating cell growth, apoptosis, and migration." (PMID 32104682, 2020). "In the prostate cancer DU145 cell line, also generated from adenocarcinoma, it has been reported that the upregulation of SERPINE1 (a serine protease inhibitor) diminishes cell proliferation and this effect is induced via activation of the AKT pathway after silencing the transcription factor ELK3." (PMID 38542079, 2024). "However, the molecular mechanisms of how ELK3 induces chemoresistance in prostate cancer (PCa) have not been elucidated." (PMID 38632244, 2024). "However, the role of ELK3 in prostate cancer cells and its mechanism are not fully understood." (PMID 32104682, 2020).
colorectal cancer (5 papers, 2020 to 2025). A primary or metastatic malignant neoplasm that affects the colon or rectum. "Accumulating evidence suggests that ELK3 is implicated in the development of anticancer drug resistance, such as resistance to doxorubicin and oxaliplatin treatment in breast and colorectal cancer, respectively." (PMID 38632244, 2024). "LINC00525 enhanced the stemness and chemoresistance of colorectal cancer through the miR-507/ELK3 axis." (PMID 32411181, 2020). "While RHBDD1 promotes colorectal cancer (CRC) via TGFα/EGFR/ERK signaling, our study reveals a distinct mechanism in ESCC, where RHBDD1 enhances invasion by activating Wnt/β-catenin via ELK3." (PMID 40787199, 2025).
melanoma (5 papers, 2020 to 2024). A malignant, usually aggressive tumor composed of atypical, neoplastic melanocytes. "Moreover, PAX7 and Elk3 are significant in the context of melanoma and neuroblastoma, both of which originate from neural crest-derived cells." (PMID 39404397, 2024). "Since melanocytes share a common embryonic origin with neural crest cells, pathways involving PAX7 and Elk3 may play a role in melanoma progression." (PMID 39404397, 2024). "Elk3, which regulates the transition of progenitors to definitive neural crest cells, might similarly influence melanocyte dynamics and melanoma development." (PMID 39404397, 2024). "In particular, ELK3, ETS1, ETV1, ETV4, ETV5, and SPI1 were significantly upregulated in melanoma, whereas EHF, ELF3, ELF5, ERG, ETS2, ETV7, and SPDEF were significantly downregulated in the tumor." (PMID 33424867, 2020). "Moreover, the upregulation of ELK3 expression by LINC00662, a noncoding RNA, promotes melanoma cell proliferation, migration, and invasion." (PMID 38632244, 2024). "In addition, no studies have reported on the expression and function of ELK3, ETV5 ELF3, ELF5, ETS2, and SPDEF in melanoma." (PMID 33424867, 2020).
pancreatic cancer (5 papers, 2016 to 2022). "Our results showed that ELK3 was associated with malignant progression of pancreatic cancer." (PMID 34409034, 2021). "The mRNA level of ELK3 was significantly upregulated in pancreatic cancer tissues in two datasets (Badea Pancreas Statistics, P = 6.36E-9; Segara Pancreas Statistics, P = 8.46E-5)." (PMID 34409034, 2021). "Given the importance of ELK3 in these processes, we first examined the expression of ELK3 in GEO and TCGA databases, and found ELK3 was overexpressed in pancreatic cancer tissues compared with adjacent normal tissues." (PMID 34409034, 2021). "To verify the function of ELK3 in pancreatic tumor growth and metastasis in vivo, we injected pancreatic cancer cells with stable knockdown or overexpression of ELK3 into the armpit or tail vein of nude mice." (PMID 34409034, 2021). "To sum up, we concluded that ZEB1 binds to the region between −641 and −631 bp of the ELK3 promoter to activate its’ transcriptional activity in pancreatic cancer." (PMID 34409034, 2021). "ELK3 expression was significantly higher in pancreatic cancer tissues of T3 stage, N1stage, distant metastasis M1 stage and AJCC stage IIB-IV than in these of T1–T2 stage, N0 stage, M1 stage and AJCC-IIA stage, respectively (P < 0.05 for all)." (PMID 34409034, 2021). "In summary, our study illustrated the oncogenic role of ELK3 in pancreatic cancer cell proliferation, migration and invasion." (PMID 34409034, 2021). "Collectively, our data demonstrated the effects of ELK3 on β-catenin signaling, indicating the important roles of ELK3 in pancreatic cancer progression and EMT process." (PMID 34409034, 2021). "The result showed that ELK3 was overexpressed in several pancreatic cancer cells compared with normal pancreatic ductal epithelial cell (HPDE6-c7)." (PMID 34409034, 2021). "Taken together, these in vivo results suggest that ELK3 plays an important role in pancreatic tumor growth and metastasis." (PMID 34409034, 2021). "On the contrary, some researchers reported that ELK3 was less expressed in cervical cancer and pancreatic cancer, and its ectopic expression inhibited the growth of these cancer cells." (PMID 32104682, 2020). "ELK3 strongly represses transcription of the proto-oncogene, c-fos, and overexpression of ELK3 inhibits the proliferation of pancreatic cancer cells." (PMID 27556500, 2016). "Correlations between ELK3 and clinicopathologic parameters in pancreatic cancer patients." (PMID 34409034, 2021). "In the present study, we first identified the upregulation of ELK3 in pancreatic cancer tissues." (PMID 34409034, 2021). "Moreover, nearly 64.3% of pancreatic cancer samples with higher expression of ZEB1 presented stronger ELK3 staining, while approximately 71.2% of those with lower ZEB1 expression exhibited weaker ELK3 staining." (PMID 34409034, 2021). "Considering the importance of β-catenin signaling in the development of cancer and EMT process, we were inspired to explore whether ELK3 could regulate the Wnt/β-catenin signaling pathway in pancreatic cancer." (PMID 34409034, 2021). "However, in contrast, ELK3 over-expression inhibited the cell cycle progression of pancreatic carcinoma cells, resulting in an increase in G0/G1 phase fraction and a decrease in S phase fraction." (PMID 32104682, 2020). "Meanwhile, both were found to be overexpressed in pancreatic cancer tissues and high ZEB1 and ELK3 expression were both closely associated with patients’ clinicopathological features and worse overall survival, indicating ZEB1 and ELK3 may be efficient diagnostic and therapeutic targets in PDAC." (PMID 34409034, 2021).